CFP (complement factor properdin)
Diseases named in the same sentence as CFP in open-access papers (continued):
Sharing a sentence is not in itself a finding about the gene and the disease.
malaria (1 paper, 2025). Malaria is a serious and sometimes fatal disease caused by a parasite that commonly infects a certain type of mosquito which feeds on humans. "Between August 2020 and March 2022, there were 2112 malaria cases in cohort children in the CoZo health zone (491, 732, and 889 cases in the Py-CFP LLIN arm, Py-PPF LLIN arm, and standard LLIN arm, respectively)." (PMID 40383756, 2025).
malignant glioma (1 paper, 2016). A grade III or grade IV glioma arising from the central nervous system. "Tumor growth and micro-environmental studies can be performed by implanting reporter gene expressing malignant glioma cells (i.e. various fluorescent protein expressions such as GFP, RFP, YFP, CFP and others)." (PMID 26673818, 2016).
medulloblastoma (1 paper, 2016). A malignant, invasive embryonal neoplasm arising from the cerebellum. "In order to enable the identification of novel radiosensitizers for medulloblastoma, a small molecule screen was performed using DAOY medulloblastoma cells that were transduced with a lentiviral Gaussia luciferase (Gluc) vector co-expressing the fluorescent ‘Cerulean’ (CFP) reporter." (PMID 26967057, 2016).
meningitis (1 paper, 2024). A disorder characterized by acute inflammation of the meninges of the brain and/or spinal cord. "It has been reported that mutations in the exon of the CFP gene on the X chromosome can cause meningitis." (PMID 39881721, 2024).
myeloid leukemia (1 paper, 2015). A clonal proliferation of myeloid cells and their precursors in the bone marrow, peripheral blood, and spleen. "The myeloid leukemia K562 cells that do not express endogenous β2 integrins were transfected with expression plasmids of integrin αL and Dok1-CFP (CFP fused to the C-terminus of Dok-1) and integrin β2-YFP wild-type or S745G/S756G or S745E/S756E." (PMID 26108885, 2015).
neuropathy (1 paper, 2021). A disorder affecting the nervous system that manifests with pain, tingling, numbness, and/or muscle weakness. "In our study, we were the first to demonstrate an increase in the expression of genes regulating the complement system such as CFP encoding properdin and CFD encoding Factor D in patients with neuropathy." (PMID 34640602, 2021).
osteosarcoma (1 paper, 2022). A usually aggressive malignant bone-forming mesenchymal neoplasm, predominantly affecting adolescents and young adults. "Visualization of PR homodimers and heterodimers have been reported as showing increased FRET signal upon progestin ORG2058 treatment in human osteosarcoma cell line U-2 OS cells transfected with CFP-PRA, YFP-PRA, CFP-PRB, and YFP-PRB, respectively." (PMID 37435453, 2022).
pulmonary TB (1 paper, 2011). "The ALS method was validated in a larger cohort (n = 212) of patients with suspicion of pulmonary TB using multiple antigens (BCG, LAM, TB15.3, TB51A, CFP10-ESAT6-A, CFP, CW) from Mycobacterium tuberculosis." (PMID 21283655, 2011).
renal fibrosis (1 paper, 2022). A final common manifestation of a wide variety of chronic kidney diseases characterized by glomerulosclerosis and tubulointerstitial fibrosis. "Histological analyses also revealed that CFP and liraglutide treatment reduced lipid accumulation, improved the morphology of the renal glomerulus and mesangial cells, as well as attenuated renal fibrosis." (PMID 35958251, 2022).
septicemia (1 paper, 2022). "In this study, most patients with septicemia caused by ceftriaxone-resistant Enterobacteriaceae received CFP–SUL 1 g/1 g Q12H treatment." (PMID 35453212, 2022). "On the other hand, in the CFP–SUL 2 g/2 g group, 40 patients (39.2%) had septicemia caused by Acinetobacter spp." (PMID 35453212, 2022). "Regarding clinical outcomes of patients with septicemia caused by Gram-negative organisms, the 14-day and 30-day all-cause mortality seemed to be higher in the CFP–SUL 1 g/1 g group than in the CFP–SUL 2 g/2 g group." (PMID 35453212, 2022). "Therefore, the goal of our study was to investigate differences in clinical outcomes and side effects between administration of CFP–SUL 1 g/1 g and 2 g/2 g Q12H in patients with septicemia caused by Gram-negative microorganisms who had impaired renal function." (PMID 35453212, 2022).
vitiligo (1 paper, 2021). Generalized well circumscribed patches of leukoderma that are generally distributed over symmetric body locations and is due to autoimmune destruction of melanocytes. "To investigate whether CCL17 is critical for depigmentation, we adoptively transferred CFP‐PMEL CD8+ T cells into wild type (WT) or CCL17‐deficient (CCL17−/−) KRT14‐Kitl*4XTG2Bjl (Krt14‐Kitl*) mice to induce vitiligo." (PMID 34077992, 2021). "To investigate whether CCR4 is critical for depigmentation, we adoptively transferred CFP‐PMEL CD8+ T cells (WT) or CCR4‐deficient CFP‐PMEL CD8+ T cells (CCR4−/−) into KRT14‐Kitl*4XTG2Bjl (Krt14‐Kitl*) mice to induce vitiligo." (PMID 34077992, 2021).
infection (34 papers, 2009 to 2025). The state of being infected such as from the introduction of a foreign agent such as serum, vaccine, antigenic substance or organism. "Huh7 cells were transfected with a panel of plasmids encoding wild-type or DN Rab proteins as GFP/CFP fusions prior to infection with JFH-1 or J6/JFH-1luc." (PMID 27226379, 2016). "The CTCF sgRNA domain library was cloned into a lentiviral vector with puromycin resistance and CFP fluorescence followed by infection at a low M.O.I. (less than 0.3) into a SEM B-ALL cell line stably expressing Cas9." (PMID 36698211, 2023). "Sublethal chlorfenapyr dose induced significantly lower prevalence of infection than the lower anti-malarial dose (6.6% [2.7–14.9] for CFP vs. 24% [16.1–34.9] for A/L, OR [95% CI] = 0.22 [0.06–0.7], p < 0.012)." (PMID 37946208, 2023). "This allowed us to distinguish between acute infection, where both fluorophores are expressed, to quiescent infection in which only the CFP is expressed." (PMID 35862979, 2022). "Infection of leaves with recombinant virus expressing CFP ligated with a viral RNA polymerase NIB (CFP::NIB), combined with a yeast two-hybrid assay and BiFC analysis, suggested that NbEXPA1 acts in the viral replication complex via interaction with NIB." (PMID 31212892, 2019). "To examine if TLR7/8/MyD88 signaling affects intracellular Mav growth we next quantified Mav-CFP intensities across infected macrophages at the single cell level 4 hours and 3 days post infection." (PMID 28806745, 2017). "Parasite infection promotes the nuclear localization of both NF-κB proteins Dif and Dorsal in wild type fat body (Cg>CFP-Dif, Cg>GFP-Dorsal) and blood cells." (PMID 21203476, 2010). "In contrast to the situation in culture, however, Δprocyclin was unable to maintain its equilibrium with CFP#5 in the fly and was competed out within one cycle of infection." (PMID 19223969, 2009). "We performed single-round infection experiments with VSV-G-pseudotyped HIV reporter virus expressing GFP or CFP." (PMID 19668336, 2009). "Gag-CFP forms discrete puncta along the plasma membrane, in the cytoplasm, and in the nucleus, mimicking the distribution of Gag during infection (1, 2, 11, –, 13, 15, 30, 31)." (PMID 32265329, 2020). "The CFP-level and thus the total number of Mav increased ten-fold over 3 days of infection." (PMID 28806745, 2017). "Moreover, we observed a 3-fold decrease in the number of CFP bacteria per cell in the case of superinfection, when compared with the infection of cells with E. coli-CFP alone." (PMID 22911692, 2012). "Sixteen cattle complement genes, including complement C2, complement factor B (CFB), complement C1r (C1R), C1R-like, C3aR1, complement factor properdin (CFP) and complement factor I (CFI) were upregulated two- to 10.6-fold in response to the infection." (PMID 41398915, 2025). "CFP, YFP, and FRET images in the soma of 14 DIV cultured hippocampal neurons were acquired 36 hr after infection, and the emission ratio was calculated." (PMID 37358072, 2023). "Following infection, unvaccinated mice also had a high frequency of T cells producing IFN-γ in response to stimulation with M. tuberculosis CFP." (PMID 34793507, 2021). "Two months post-infection, CFB, C3, C3aR, and C5aR1 expression remained higher than in controls, while CFP upregulation was transient." (PMID 33613523, 2020). "To further determine γb targeting to the PD during infection, we plasmolyzed N. benthamiana epidermal leaf cells that had been co-infiltrated with A. tumefaciens expressing BSMVγb-GFP infectious RNA plasmids and the PD marker CFP-PDLP." (PMID 32730331, 2020). "In addition, at least 11 genes implicated in complement activation were significantly impacted by infection in CHB, such as complement factor properdin (CFP, 2.8 fold), complement component 7 (C7, 4.2 fold), and complement factor I (CFI, 12.1 fold)." (PMID 27197554, 2016).
infection (continued). "Each individual donor animal was then removed and examined for stage of infection and whether it had gaps in IFB-2::CFP localization." (PMID 21949650, 2011). "Interestingly, when we analyzed the terminal web in act-5 RNAi-treated animals we found gaps in IFB-2::CFP that appeared in the absence of infection." (PMID 21949650, 2011). "THY1 (thy-1 cell surface antigen) and CFP (complement factor properdin), which showed changes of less than 2-fold in the microarray results, and HIRF (HPS infection related factor), which was not annotated in the analysis of GO, were also selected for QPCR confirmation." (PMID 19196461, 2009).
tumor (33 papers, 2011 to 2025). "Analysis of 13,023 genes for mutations between primary breast tumors and normal tissue revealed mutations at a significant frequency in the properdin (CFP) gene, hinting at mutants contribution to tumor progression." (PMID 33542722, 2020). "Furthermore, gene markers of infiltrating immune cells exhibited different CFP-related immune infiltration patterns such as tumor-associated-macrophages (TAMs)." (PMID 33976747, 2021). "Here, as we already used three fluorescent proteins to demarcate tumor cells (CFP and mCherry) and vessels (GFP), ideally a compatible method for label‐free visualization of blood flow is needed." (PMID 40557748, 2025). "Compared with the saline, CFP resulted in slight tumour inhibition due to the CDT effect, but the best primary tumour elimination was in mice receiving CFP + US." (PMID 39537767, 2025). "To clarify the mechanism by which CFP knockdown led to tumor growth inhibition, we performed immunofluorescence assays on tumor tissues to detect cell proliferation and apoptosis." (PMID 37735441, 2023). "In order to determine the expression levels of CFP in different tumor tissues, we analyzed the expression levels of CFP in the Oncomine database." (PMID 33976747, 2021). "The analysis results showed that CFP expression in 29 Tumor types was significantly correlated with tumor purity." (PMID 33976747, 2021). "TIMER and GEPIA database were used to explore the potential relationship between CFP expression and tumor immune invasion." (PMID 33976747, 2021). "According to the TIMER tool, CFP gene expression moderately, but significantly and negatively, correlated with the tumor purity (p < 0.05)." (PMID 33542722, 2020). "Using a synergy of additional PD-L1 checkpoint blockade achieved the most significant abscopal effect – with treatments of “CFP+anti-PD-L1” and “CFP + US+anti-PD-L1” resulting in an outstanding suppression on primary tumour growth, with a tumour growth inhibition of 46.7% and 66.3%, respectively." (PMID 39537767, 2025). "Also, the expression levels of CFP were correlated with many sets of immune markers of tumor immune cells, such as those of CD8+ T cells, CD4+ T cells, B cells, M2 macrophages, neutrophils, DCs, Th1 cells, Th2 cells, and T cell exhaustion in HCC." (PMID 34813686, 2022). "Therefore, we believed the expression of CFP was correlated with tumor immune cells in HCC patients." (PMID 34813686, 2022). "Previous studies have shown that CFP is a ligand of NK cell activation receptor NKp46 18, indicating that CFP can not only remove tumor cells through complement activation, but also promote the removal of tumor cells by promoting phagocytosis and removal of target cells without activated complement." (PMID 33976747, 2021). "Therefore, we further analyzed the correlations of CFP expression and B cell/macrophage markers in tumor tissues of LUAD and STAD in GEPIA." (PMID 33976747, 2021). "In tumor microenvironment, CFP may be involved in the regulation of tumor-related macrophages (TAMs), dendritic cells (DCs), T cell failure and Tregs." (PMID 33976747, 2021). "Therefore, the potential relationship between CFP and tumor prognosis and immunologic invasion was analyzed in our study." (PMID 33976747, 2021). "CFP expression negatively correlated with the tumor purity in all cancers." (PMID 33542722, 2020). "Strikingly, the transcriptional signature of AsPC1-AKT tumors originating from either lean or obese mice significantly overlapped with that of Obese-CFP, when compared to Lean-CFP tumors, suggesting that enhanced in vivo tumor growth is a strong inducer of nitrogen metabolism and the urea cycle." (PMID 28808255, 2017). "Same numbers of YFP and CFP tumor cells arrived at the tail at 1, 6, and 12 hpi, but more TRCs extravasated than control cells at 12 hpi and at 24 hpi, suggesting that differential targeting in metastasis could be explained largely by efficient extravasation of TRCs alone." (PMID 26787224, 2016).
tumor (continued). "We further studied the relationship between mRNA expression levels of C1R, C6, C7, CFP, CFHR3, and tumor stages in HCC patients by using the UALCAN database since these genes were considered to have prognostic value." (PMID 34813686, 2022). "The results showed that CFP is closely related to the prognosis of STAD and LYAD, and potentially interact with tumor immune infiltration." (PMID 33976747, 2021). "This analysis revealed a significant increase in the CFP-YFP ratios of both C26 and SW480 tumor cells after docetaxel treatment when compared to pre-treated conditions and vehicle (PBS)-control, indicating there is an increase in caspase-3 activity." (PMID 23691140, 2013). "C1R, C2, C6, C8, MBL, CFP and CFHR were downregulated in HCC and exhibited tumour-suppressive effects; thus, they could serve as prognostic markers for HCC." (PMID 36341431, 2022). "Also, C1R, C6, C7, and CFHR3 presented correlations with tumor grades and cancer stage in HCC patients, while CFP presented correlations with the immune markers of tumor immune cells in HCC." (PMID 34813686, 2022). "There were individual differences in the process of caspase-3 activity in tumor cells; the ratio of the fluorescent signal in the FRET channel to the CFP channel was decreased from a maximum to a minimum value around 20 minutes in most of the tumor cells, and in some tumor cells it lasted for 1 h." (PMID 33391470, 2021). "Therefore, it is reasonable to speculate that CFP-mediated changes in the function of immune cells, in particular, the functions of T-lymphocyte activation and neutrophil adhesion, may be closely related to immune infiltration, thereby affecting the tumor microenvironment." (PMID 33976747, 2021). "Based on the TIMER analysis, CFP expression showed a significantly weak negative correlation with tumor purity (p < 0.05)." (PMID 33542722, 2020). "With respect to immune infiltration, CFP gene expression showed a partial but significant and negative relationship with the tumor purity (p < 0.05)." (PMID 33542722, 2020). "Notice however that although the histo-pathological examination revealed typical tumor morphology, the expression of CFP (and the concomitant oncogene) was no longer detected." (PMID 28835665, 2017). "A similar reduction was seen in Sox2 positive non-stem tumor cells (CFP cells) from an initial population of 7.1 percent in culture to 0.1 percent in the tumor." (PMID 21961046, 2011). "Thus, CFP-mediated SDT/CDT could efficiently induce ICD of tumor cells, which would lead to a boost in antitumor immunity in 4T1 tumor–bearing mice after the combination with immune checkpoint blockade (anti-PD-L1)." (PMID 34660560, 2021). "The CFP showed a catalase-like activity to produce a hydroxyl radical (·OH) for CDT and catalyze the decomposition of H2O2 in a tumor microenvironment to form O2 to relieve tumor hypoxia, which enabled the generation of a high level of 1O2 under US irradiation to achieve effective SDT." (PMID 34660560, 2021). "However, few researches had been done on the relationship between CFP and tumor so far with more studies are focused on non-neoplastic disease." (PMID 33976747, 2021). "We also assessed proliferation using the M-phase marker phosphorylated-histone H3 (PH3) and found that 1.7 percent of CSCs and their descendants (YFP cells) were actively in M-phase as compared with less than 0.01 percent of non-stem tumor cells and their descendants (CFP cells)." (PMID 21961046, 2011). "Second, even though the expression of CFP was found to be related to immune cell infiltration and the patient survival in tumor, this study could not prove that CFP affected patient survival through immune infiltration, which needs to be verified by in vivo and in vitro experiments." (PMID 33976747, 2021). "The results showed that the mRNA expression levels of C1R, C6, C7, and CFHR3 were correlated with the tumor grade of HCC patients, while only CFP was not correlated with the tumor grade of HCC patients." (PMID 34813686, 2022).
tumor (continued). "The results showed that the expression levels of C1R, C6, and CFHR3 were correlated with the tumor stage of HCC patients, while the expression levels of C7 and CFP were not correlated with the tumor stage of HCC patients." (PMID 34813686, 2022).